CCL2 (C-C motif chemokine ligand 2)
Diseases named in the same sentence as CCL2 in open-access papers (continued):
Sharing a sentence is not in itself a finding about the gene and the disease.
gastric cancer (continued). "Furthermore, we performed the ROC curve to investigate the predictive value of gastric cancer, and results showed that VEGF*CCL2 could provide higher accuracy for distinguishing gastric cancer patients from controls than alone VEGF or CCL." (PMID 23697837, 2013). "CCL2 rs4586 was previously shown to be involved in several other cancer types, including CRC, locoregional gastric cancer (LRGC), and BC." (PMID 38001676, 2023). "Studies have demonstrated that phosphorylation of Akt and mTOR was increased in DDP-resistant gastric cancer cells and inhibition of PI3K/Akt pathway significantly attenuated CCL2-mediated DDP-resistance in gastric cancer." (PMID 33362566, 2020). "CSF1R of CD8 + Tcell, CCL2, VSIG4 of TAM, NRP1, TGFB1 of Th1 cell presented significantly correlate with PCOLCE expression in gastric cancer (P < 0.001; Cor value ≥ 0.40)." (PMID 33392251, 2020). "And CSF1R of CD8 + Tcell, CCL2, VSIG4 of M2 Macrophage, NRP1 of Th1, TGFB1 of Treg cell presented strong correction with PCOLCE expression in gastric cancer (P < 0.001; Cor value ≥ 0.40)." (PMID 33392251, 2020). "The serum values of CCL2, CCL18, and VEGF in gastric cancers were 25.05 ± 1.22 (pg/ml), 115.94 ± 22.56 (pg/ml), and 132.92 ± 10.50 (pg/ml), respectively." (PMID 23697837, 2013). "In the current study, we found that the serum levels of CCL2, CCL18, and VEGF markedly increased in gastric cancer group compared to control group." (PMID 23697837, 2013). "The preoperative serum levels of CCL2, CCL18 and VEGF in gastric cancer patients were significantly higher than that of controls (P <0.001, P <0.001, and P <0.001, respectively)." (PMID 23697837, 2013). "The aim of this study was to investigate the relationship between the preoperative serum levels of CCL2, CCL18, and VEGF, and the clinicopathological factors in patients with gastric cancer." (PMID 23697837, 2013). "Based on public omics data, it was also found that some of these biomarkers showed significant changes in the progression from gastritis to dysplasia and gastric cancer, and were reported to participant in the progression of gastric cancer, such as LEP, CCL2, CD14 and TNF." (PMID 39367502, 2024). "Thus, we measured the concentration of CCL2, CCL18, and VEGF in a series of 60 serum samples from gastric cancer." (PMID 23697837, 2013). "Preoperative serum levels of CCL2 and VEGF could play a crucial role in predicting the presence and progression of gastric cancer." (PMID 23697837, 2013). "Notably, they established a stable CCL2-overexpressing HER2+ gastric cancer cell line and found that tumor cell-derived CCL2 had no direct effect on trastuzumab resistance." (PMID 36077785, 2022). "Our study found that 50 μM of DIM (corresponding to IC50 in gastric cancer cell lines) had almost no lethal effect on GC-MSCs, but could activate the NF-κB signaling pathway and increase the expression of CCL2, IL-6, IL-8, TGF-β." (PMID 33842314, 2021). "Concerning chemokine receptors and chemokines, the expression of the chemokines CCL2 and CXCL12 were increased in nodal positive gastric cancer compared to nodal negative cases." (PMID 20386750, 2010).
osteoarthritis (61 papers, 2010 to 2025). A noninflammatory degenerative joint disease occurring chiefly in older persons, characterized by degeneration of the articular cartilage, hypertrophy of bone at the margins and changes in the synovial membrane. "Strikingly, monocytes are also involved in osteoarthritis, as monocyte recruitment causes cartilage destruction mediated by CCL2/CCR2 in experimental osteoarthritis." (PMID 40067374, 2025). "Spontaneous secretion of some adipocytokines (MMP-3 and/or TNF, CCL2/MCP-1, IL-1Ra) was higher in osteoarthritis than rheumatoid ATs and probably caused by weaker anti-inflammatory treatment of OA patients." (PMID 30280295, 2019). "Chemokine ligand 2 (CCL2), also known as monocyte chemoattractant protein-1 (MCP-1), belongs to the CC chemokine family that is associated with the disease status and outcomes of osteoarthritis (OA)." (PMID 23185512, 2012). "Osteoarthritis (OA) is characterized by a complex interplay of molecular signals orchestrated by the CCL2/CCR2 axis." (PMID 39076996, 2024). "CCL2 is a well-known mediator of spinal synaptic transmission and pain in osteoarthritis; therefore, we wanted to test if inhibition of Jnk signaling in InfA populations would also affect pain in PTOA mice." (PMID 38368390, 2024). "CCL2 is particularly relevant in the context of osteoarthritis development following IAF as the CCL2/CCR2 signaling axis is a potent mediator both pain and macrophage chemotaxis into the injured tissue." (PMID 37400744, 2023). "CCL2-mediated macrophage infiltration in articular tissues plays a pivotal role in the development of the osteoarthritis (OA)." (PMID 27129293, 2016). "The miR-33/CCL2 axis in the chondrocytes regulates monocyte chemotaxis, providing a potential mechanism of macrophage infiltration in osteoarthritis (OA)." (PMID 27129293, 2016). "In a recent meta-analysis study, CCL2 was identified as an important marker for the progression of osteoarthritis (OA) with the authors concluding that it may serve as a potential biomarker for the diagnosis of OA." (PMID 34492036, 2021). "Several other studies showed an enhanced CCL2 level in patients with osteoarthritis." (PMID 32189997, 2020). "It was reported that monocytes recruited via CCL2/CCR2, were related to immune activation and inflammation to propagate inflammation and tissue damage in osteoarthritis (OA)." (PMID 32626718, 2020). "Targeting of CCL2 and CCR2 might be a potential treatment of osteoarthritis (OA); in vivo findings from a murine OA model indicated that selective targeting of CCL2/CCR2, rather than CCL5/CCR5, was a viable therapeutic strategy." (PMID 37457301, 2023). "Monocytes recruited via Ccl2/Ccr2, rather than Ccl5/Ccr5, propagate inflammation and tissue damage in osteoarthritis, thereby representing a promising therapeutic approach." (PMID 34917083, 2021). "CCL2, a ligand for CCR2, is an inflammatory chemokine that is highly present in the serum of patients with RA relative to the serum of those with osteoarthritis, and a positive correlation has been reported between serum CCR2 concentration and RA disease activity." (PMID 27267914, 2016). "In our study, catabolic genes, including MMP-3 and -9 and ADAMTS5, and the proinflammatory cytokines, including CCL-2 and-5 and CXCL1, were also inhibited by DHA treatment, suggesting the potential role of DHA in maintaining cellular homeostasis and treating osteoarthritis." (PMID 27941926, 2016). "Interestingly, DRG NIS-lncRNA expression was not altered after peripheral inflammation, whereas Ccl2 mRNA and CCL2 protein were upregulated in innervating DRGs following induction of osteoarthritis." (PMID 35775484, 2022). "In contrast, differences between the synovial fluid levels of CCL2 and CCL5 in equine osteoarthritis (OA)-affected or healthy joints were not reported." (PMID 40496923, 2025).
osteoarthritis (continued). "Interestingly, another study found that mice lacking C-C motif chemokine ligand 2 (CCL2) or C-C motif chemokine receptor 2 (CCR2), but not CCL5 or CCR5, were protected against osteoarthritis with reduced monocyte/macrophage recruitment." (PMID 40860192, 2025). "At the same time, their studies showed that the level of CCL2 in the synovial fluid of OA patients was significantly higher than that of ordinary people (CCL2/CCR2, but not CCL5/CCR5, mediates monocyte recruitment, and utilization destruction in osteoarthritis)." (PMID 36619785, 2022).
tuberculosis (59 papers, 2005 to 2026). A chronic, recurrent infection caused by the bacterium Mycobacterium tuberculosis. "The C-C motif chemokine ligand-2 (CCL2) was evidenced to be associated with tuberculosis susceptibility in some ethnic groups." (PMID 33381602, 2020). "-2518G allele produces less CCL2 compared to A allele which leads to improper Th1 response and makes a host susceptible for tuberculosis." (PMID 33381602, 2020). "-2518G allele is responsible for lower production of CCL2 which leads to lower Th1 cytokines, hence leading to defective Th1 response which makes a host susceptible for tuberculosis." (PMID 33381602, 2020). "Although a number of reports have been published suggesting the role of CCL2 gene polymorphism in different populations, the findings are often contradictory based on the ethnicity, population, and type of tuberculosis." (PMID 33381602, 2020). "This study reported a significant association of the CCL2-2518 GG and -362 CC genotype with tuberculosis." (PMID 33381602, 2020). "Subset analyses identified CCL2 as an additional risk factor for tuberculosis (rs1024611; OR = 0.79 [0.72–0.88])." (PMID 26524966, 2015). "In the mouse model of tuberculosis, Ccl2 knock-out mice are significantly more susceptible to M. tuberculosis than their wild type littermates." (PMID 23350010, 2013). "In addition, WT1 gene from GWAS studies, implied in susceptibility to tuberculosis, has been described to be under control of CCL2, which seems to be having target-responsive cytocidal activity on WT1-specific mechanisms." (PMID 26524966, 2015). "As with many other CC chemokines, the CCL2 gene is located on chromosome 17q11.2 in humans which has been linked to susceptibility to tuberculosis and includes genes coding for several chemokines where CCL2 clusters together with the nitric oxide synthase 2A (NOS2A) and CCL3-5 genes." (PMID 21556333, 2011). "Through differential gene expression analysis, clustering, and enrichment analysis, we identified 13 key biomarkers, including CCL2, SLC11A1, CD209, HLA-DQA1, and TIRAP, which are strongly associated with immune responses in tuberculosis." (PMID 40565607, 2025). "In parallel, the monocyte-attracting chemokines CCL2, CCL8, and CCL7, associated with septic shock and tuberculosis, were elevated supporting the role of monocytes in disease pathogenesis." (PMID 33239683, 2020). "One of these studies was an outpatient cohort study that followed participants with HIV-associated tuberculosis and showed that higher pre-ART levels of MCP-1/CCL2, eotaxin, IL-10, TNF-α, and IL-6 were associated with 6-month mortality." (PMID 31276515, 2019). "The presence of the TCRαβ in mouse macrophages offers the possibility to study the role of the TNF/ TCRαβ/ CCL2 regulatory axis we identified in human macrophages in tuberculosis in vivo." (PMID 22114556, 2011). "Relationship between CCL2 rs4586 polymorphisms and pediatric tuberculosis (TB), stratified by sex." (PMID 21556333, 2011). "We have also previously reported that among the several endogenously and exogenously activated chemokines CCL2 is elevated in the more severe form of tuberculosis." (PMID 21991356, 2011). "CCL2 is essential for granuloma formation and plays a critical role in protection against tuberculosis in the murine model." (PMID 20041183, 2009). "CCL2 is essential for recruitment of monocytes and T cells and has been shown to play a role in protection against tuberculosis." (PMID 16001981, 2005). "Our study is based on a population from the northern part of India, and no report on the CCL2 gene polymorphism is available for this region in relation to tuberculosis." (PMID 33381602, 2020). "Additionally, we established a role of CCL2 in tuberculosis, by including only a subset of methodologically better studies, where controls were of known exposure." (PMID 26524966, 2015). "CCL-2 levels in plasma in relation to infection and disease in tuberculosis." (PMID 21991356, 2011).
tuberculosis (continued). "Larger scale studies are required to further define the role of CCL2 in clinical tuberculosis." (PMID 20041183, 2009). "Raised CCL2 activation in tuberculosis correlates with previous studies." (PMID 16001981, 2005). "The biological role of CCL-2 in tuberculosis has been addressed in a previous study where the investigators have shown that stimulation of healthy monocytes from -2518GG with Mycobacterium tuberculosis antigens yielded higher CCL-2 levels and lower IL-12p40 compared with healthy -2518AA genotype." (PMID 21991356, 2011). "We propose that CCL2 could be a useful adjunct marker of severity in tuberculosis." (PMID 20041183, 2009). "M. tuberculosis –induced CCL2 was significantly greater in PBMCs of TB patients as compared with both TST- and TST+ ECs (p<0.001)." (PMID 20041183, 2009). "The present study for the first time showed that CCL2 has a positive correlation with IL-12 and Th1 cytokines such as IFN-γ and TNF-α and hence essential for proper Th1 response against tuberculosis." (PMID 33381602, 2020). "Both M. tuberculosis and BCG elicited an increase in CCL2 in TB patients as compared with controls." (PMID 20041183, 2009). "Increased levels of CCL2, CXCL8 and TNFα are reported in tuberculosis but their significance in different forms of tuberculosis is as yet unclear." (PMID 16001981, 2005). "Human alveolar macrophages produced CCL2 in a PGL-dependent fashion following infection, arguing for the potential of PGL-blocking interventions or PGL-targeting vaccine strategies in the prevention of tuberculosis." (PMID 28844797, 2017). "Chemokine (C-C motif) ligand 2 CCL2/MCP-1 is among the key signaling molecules of innate immunity; in particular, it is involved in recruitment of mononuclear and other cells in response to infection, including tuberculosis (TB) and is essential for granuloma formation." (PMID 21556333, 2011). "Circulating serum levels of CXCL8 and TNFα were raised in all tuberculosis patients, while CCL2 levels were not." (PMID 16001981, 2005). "We subsequently investigated LPS-induced CCL2, CXCL8 and TNFα in tuberculosis patients." (PMID 16001981, 2005). "For example, the plasma levels of IL-18, CCL-2, and CXCL10 differed depending on whether patients developed TB IRIS without a previous episode (unmasking IRIS) or developed it as an unexpected worsening of tuberculosis (paradoxical IRIS)." (PMID 23688318, 2013). "Increased M. tuberculosis- and M. bovis BCG - induced CCL2 and IL10 and decreased IFNγ responses in TB patients." (PMID 20041183, 2009). "When responses between patients with pulmonary and extrapulmonary TB were compared, M. tuberculosis and BCG-induced CCL2 secretion was found to be increased in patients with pulmonary TB as compared with those with less severe localized extrapulmonary TB." (PMID 20041183, 2009). "CCL2 responses to M. tuberculosis and BCG showed a parallel trend although the magnitude of secretion from TB patients in response to M. tuberculosis was significantly greater as compared with BCG (p<0.001)." (PMID 20041183, 2009). "Leucocyte activating chemokines such as CCL2, CCL3, and CXCL8 together with proinflammatory IFNγ, TNFα and downmodulatory IL10 play a central role in the restriction of M. tuberculosis infections, but is unclear whether these markers are indicative of tuberculosis disease severity." (PMID 20041183, 2009). "Asymptomatic donors with no history of tuberculosis treatment (Tuberculosis Not Affected individuals; TBNA = 196) and where CCL2 genotype SNPs analysis was available, were included in the study." (PMID 21991356, 2011).
dengue (58 papers, 2007 to 2025). "In a study about the immune profile of dengue fever and parvovirosis, high levels of CCL2 tended to be associated with parvovirus B19 infection as the same way as observed herein with malaria infection." (PMID 26271921, 2015). "Even host genetic factors such as genetic variants in FcγRIIa, DC-SIGN, MHC genes, MBL2, CCL-2, TNF-alpha, etc., contribute towards the progression to severe dengue." (PMID 40880375, 2025). "After scrutinized papaya leaf juice for three days following a 24-hour viral infusion elicited a jump in CCL2/MCP-1 levels during the peak of viremia in dengue-infected AG129 mice." (PMID 36818227, 2023). "Treatment of dengue infected AG129 mice with papaya leaf juice for three consecutive days after 24h of dengue virus inoculation resulted in increased plasma CCL2/MCP-1 level during the peak of viremia." (PMID 33981215, 2021). "The importance of CCL2/MCP-1 in dengue infection has been reported in many studies involving AG129 dengue mouse model where the cytokine was found to be increased during infection." (PMID 30744623, 2019). "In dengue patients, CCL2 was increased in the plasma and positively correlated with disease severity." (PMID 25474197, 2014). "CCL2 is also present at higher levels in the serum of dengue hemorrhagic fever patients compared to dengue fever patients." (PMID 22574162, 2012). "PCR quantification of the same transcripts in patients with acute versus convalescent dengue disease showed highly elevated fold changes for CCL2, -8 and CXCL10 but a more modest enrichment of MIP-1α at fold change 3.5." (PMID 21810247, 2011). "Our results demonstrate increased levels of TNF-α and MCP-1/CCL2 in patients that evolved with either mild dengue or warning signs and severe dengue syndromes, while higher levels of IFN-ɣ, RANTES/CCL5 and IL-1β were observed only in plasma from patients presenting warning signs and severe dengue." (PMID 36569864, 2022). "CCL2 has been shown to facilitate the chemotaxis of both monocytes and T cells in vitro and has been implicated in the pathogenesis of several virus diseases including HIV, dengue and WNV." (PMID 25036379, 2014). "Comparing whole genome expression profiles between patients with acute versus convalescent dengue disease indicated significant abundance of transcripts of the chemokines CCL2 (4,287 fold), CCL8 (160 fold), CXCL10 (30 fold) and CCL3 (17 fold) during acute dengue." (PMID 21810247, 2011). "Among them, a vast panel of increased cytokines and chemokines in severe dengue, such as IFN-γ, GM-CSF, IL-10, CCL4/MIP-1β, IL-1β, CXCL8/IL-8 TNF-α, CXCL10/IP-10, CCL2/MCP-1, and IL-18." (PMID 35631030, 2022). "In our study, higher plasma levels of the proinflammatory cytokines TNF-α, IL-6 and IL-18, and the anti-inflammatory cytokine IL-10 and the chemokines CXCL8/IL-8, CCL2/MCP-1 and CXCL10/IP-10 were found in the dengue patients compared to the healthy controls." (PMID 34578370, 2021). "In dengue severe cases an increase of pro inflammatory and vasoactive cytokines as IFN-γ, TNF-α, IL-1, IL-6, IL-8 IL-10, CCL2 (MCP-1) and CCL5 is usually observed." (PMID 33692368, 2021). "Further assessment of host factors revealed that cytokines such as CCL2, CCL5, CCL20 and CXCL1, as well as adhesion molecule ICAM-1, that are involved in leukocytes infiltration were expressed higher in dengue patients in comparison to healthy individuals." (PMID 32764789, 2020). "The FCPLJ treatment has affected the regulation of four genes, CCL-2/MCP-1 (upregulated), ITGB3, ICAM1 and FN1 (downregulated), which were involved in endothelial permeability regulation during dengue virus infections." (PMID 30944031, 2019). "CCL chemokines, in particular CCL2, 3 and 4 were preferentially produced by CD16+ monocytes during the early phases of the dengue response in our assays." (PMID 22574162, 2012).